PDGFRB (platelet derived growth factor receptor beta)
Diseases named in the same sentence as PDGFRB in open-access papers (continued):
Sharing a sentence is not in itself a finding about the gene and the disease.
breast cancer (continued). "In alliance with its role in chemotherapy resistance, we also found an increase in PDGFRβ expression upon doxorubicin treatment in breast cancer cells." (PMID 30777101, 2019). "To validate the contribution of PDGFRβ in acquired resistance in this setting, we pre-treated breast cancer cells with triple combination therapy for 72 h, washed out the inhibitors and further stimulated cells with PDGF-BB ligands for a further 48 h." (PMID 30777101, 2019). "PDGFRβ expression in breast cancer has only been reported in stroma and high expression has been associated to HER2 positivity, high Ki67, high histopathologic grade, ER negativity and shorter survival." (PMID 29380207, 2018). "In breast cancer, MEK inhibition resulted in acute ERK activity loss and subsequent c-MYC degradation that induced expression and activation of PDGFRB, DDR2 and VEGFR272, an RTK combination found in patients 6 (PT) and 10 (M) of our dataset." (PMID 29743718, 2018). "The PDGFRβ axis is involved in breast cancer because tumor tissue and the surrounding stroma express PDGFRβ." (PMID 29792166, 2018). "In conclusion, we show that high expression of PDGFRα, PDGFRβ and ligand PDGF-CC is associated to several important prognostic patient and tumour characteristics in breast cancer, indicating a link to tumours with inherent biological aggressiveness." (PMID 29380207, 2018). "Some RTKs, as PDGFRβ and Axl RTKs, are emerging as mesenchymal/stem cell-specific markers in breast cancers." (PMID 28974015, 2017). "Recent evidence in a murine model of breast cancer showed that PDGFRβ+ pericytes differentially regulate tumor progression." (PMID 28878242, 2017). "PDGF isoforms exert their biological functions through binding and activation of PDGFRα and PDGFRβ, which are involved in the progression of a number of tumors, including breast cancer." (PMID 28989976, 2017). "PDGFRα and PDGFRβ expression on breast cancer and the surrounding tumor stroma has been shown to be highly correlated with tumor aggressiveness and metastasis, respectively." (PMID 27931212, 2016). "Our previous study showed that murine claudin-low mammary tumor cells expressed elevated levels of PDGFRα and PDGFRβ compared to murine luminal mammary tumor cells." (PMID 25253994, 2014). "The ability of Sunitinib and Regorafenib to inhibit breast cancer cell proliferation presumably results from inhibition of a kinase other than PDGFRβ." (PMID 25253994, 2014). "Imatinib combined with vinorelbine have been reported to enhance breast cancer cell growth inhibition via PDGFRβ signaling." (PMID 24009732, 2013). "Consistent with the western blot data, qRT-PCR analysis revealed that IGF-IR mRNA was significantly decreased in the mammary tumors following doxycycline withdrawal while the levels of PDGFRα and PDGFRβ mRNA were elevated at least 2.9-fold." (PMID 22070644, 2011). "IGF-IR independent mammary tumors, previously shown to possess characteristics associated with EMT, were found to express elevated levels of PDGFRα and PDGFRβ." (PMID 22070644, 2011). "As a first step, western blotting was performed for PDGFRα and PDGFRβ in primary mammary tumors (IGF-IR-dependent) and IGF-IR-dependent recurrent tumors of MTB-IGFIR transgenic mice." (PMID 22070644, 2011). "More than half of the lung cancers, colon cancers, breast cancer and melanomas, and one third of the prostate and ovarian cancers express PDGFRβ in the stromal cells." (PMID 27713269, 2010). "Integrin α11 also binds to PDGFRβ on CAFs, leading to increased invasion of breast cancer cells." (PMID 39780187, 2025). "However, when BM‐MSCs were treated with a nuclease‐resistant RNA aptamer targeting PDGFRβ, the signaling pathways dependent on this receptor were inhibited, leading to a significant impairment in the homing of BM‐MSCs to breast cancer cells." (PMID 39070181, 2024).
breast cancer (continued). "Sections of end-stage tumors from each of the four breast cancer mouse models and normal mammary glands were stained for fibroblasts using antibodies against PDGFRβ, αSMA and vimentin; for collagen fibers by Masson Trichrome and for epithelial cells using antibodies against E-cadherin and EpCAM." (PMID 36635273, 2023). "Additionally, the prognostic value of stromal PDGFRβ expression was more substantial in young and premenopausal patients with breast cancer." (PMID 38273859, 2023). "In addition, PDGFB/PDGFRβ were found to be highly expressed in many subtypes of breast cancer cells and tissues, and breast cancer-associated stromal cells and vasculature also exhibited positive staining of PDGFB/PDGFRβ." (PMID 35672821, 2022). "Our novel observation regarding reduced PDGFRβ and TNC expression in α11-deficient mouse skin tumors is in line with these previous findings on breast cancer and suggests that the α11/PDGFRβ/TNC axis may promote also skin carcinogenesis." (PMID 36003785, 2022). "Similarly, phosphorylation of PDGFRβ (tyrosine 75) is significantly increased in astrocytes located near breast cancer cells compared with normal astrocytes." (PMID 34122447, 2021). "Furthermore, Pdgfrβ mRNA levels in p18−/−;Brca1+/− mammary tumors strongly correlated with EMT and stem cell signatures, in agreement with the data derived from IHC and published elsewhere." (PMID 33478572, 2021). "Our murine data are also in agreement with findings in human breast cancer, showing reduced levels of PDGFRα and the concomitant increase in PDGFRβ expression as the disease progresses, which also acts as a strong marker of high-risk ductal carcinoma in situ (DCIS)." (PMID 34016130, 2021). "Moreover, one study demonstrated that collagen binding integrin α11 expressed by CAFs activates PDGFRβ/JNK signaling in breast cancer cells to promote tumor cell invasion." (PMID 32984031, 2020). "Specifically, in breast cancer, PDGFRβ accumulation is seen in the stromal components." (PMID 30777101, 2019). "Finally, we found an inverse correlation between JAK2 and PDGFRβ mRNA levels in both breast cancer TCGA and METABRIC data." (PMID 30777101, 2019). "Moreover, although not statistically significant, we found a pattern of poor survival in TCGA breast cancer patients expressing high PDGFRβ with low JAK2 levels compared to patients expressing low PDGFRβ with high JAK2 levels (HR:1.507, logrank: 0.00804)." (PMID 30777101, 2019). "The aim of the present study was to explore the expression of PDGFRα, PDGFRβ and ligand PDGF-CC in breast cancer to elucidate if these proteins are associated with molecular surrogate subtypes, type of metastatic location and prognosis in breast cancer." (PMID 29380207, 2018). "PDGFRB was found could increase glioma stem cell growth and survival, mammary tumor cells migration, however, little is known about the PDGFRB signaling in esophageal cancer cells." (PMID 28147311, 2017). "Therefore, more samples would need to be analysed in order to draw a valid conclusion for the mRNA levels of PDGFRβ in canine mammary cancer stroma." (PMID 28531107, 2017). "The finding of increased Pdgfrα phosphorylation is of interest because autocrine Pdgf action is associated with TGF-β-induced epithelial–mesenchymal transition (EMT) in MMTV-Neu mammary tumours and because increased Pdgfrα and Pdgfrβ expression occur in late-stage, invasive human breast cancers." (PMID 25200860, 2014). "This is not entirely unexpected as elevated levels of PDGFRβ have previously been associated with enhanced cell migration and invasion in breast cancer." (PMID 23820017, 2013). "Similarly, high PDGFRβ tumor stromal expression significantly correlated with more aggressive clinical behavior in patients with breast cancer, including high histopathological grade, estrogen receptor negativity, high HER2 expression and shorter survival." (PMID 23146028, 2012).
breast cancer (continued). "The potential of PDGFRβ as a predictive biomarker for treatment benefit has first been demonstrated in an IHC-based post hoc analysis of two randomized trials for adjuvant tamoxifen treatment of early breast cancer including either pre- or post-menopausal women." (PMID 38980580, 2024). "However, the application of a gene expression signature reflecting PDGFRb-activation stably indicated prognostic relevance of a high signature score for shorter recurrence free survival and/or breast cancer specific survival in four independent patient cohorts." (PMID 33661437, 2021). "Notably, Pdgfrβ and Ck14 doubly positive tumor cells were also detected in lung metastases of p18−/−;Brca1MGKO and p16−/−;Brca1MGKO mammary tumors, which demonstrated that the metastases were derived from Brca1-deficient basal-like mammary tumors with an increased Pdgfrβ expression." (PMID 33478572, 2021). "Notably, PDGFRβ expression is specifically upregulated in late-stage breast cancer cells." (PMID 33478572, 2021). "To determine whether PDGFRβ signaling blockade enhances the growth-inhibitory effect of combined MEK1/2-JAK2 inhibition (AZD6244/AZD1480) in basal-like breast cancer cells in vivo, we first tested the combination therapy using a human cell line, MDA-MB-231 xenografts in immunocompromised nude mice." (PMID 30777101, 2019). "Interestingly, stromal expression of PDGFRβ in breast cancer correlated with poor prognosis." (PMID 27128408, 2016). "In addition, imatinib has been investigated in advanced breast cancers expressing PDGFRβ." (PMID 23820017, 2013). "Additionally, PDGFRβ was found in ECs growing in a bone metastasis breast cancer model." (PMID 27713269, 2010). "In breast cancer and ovarian cancer, four CAF subpopulations, CAF-S1 to CAF-S4, were identified with many markers, such as PDGFRβ, FAP, CD29, αSMA and S100A4." (PMID 38644492, 2024). "In breast cancer, CAF markers such as FAP, α-SMA, Vimentin, FSP1, PDGFRα, PDGFRβ, Caveolin-1, and PDPN have been validated." (PMID 39519118, 2024). "In another work, they also found four CAF populations in breast cancer, but their markers were differentially expressed, CAFS1 and CAFS4 (FAP, CD29, αSMA, PDGFRβ), CAFS2 (αSMA, PDGFRβ), CAFS3 (CD29, PDGFRβ)." (PMID 38606999, 2024). "The expression of PDGFRβ in stromal cells exhibited an inverse correlation with radiation benefit, RFS, and breast cancer-specific survival." (PMID 38273859, 2023). "Since high stromal PDGFRB expression is known to be correlated with shorter survival in breast cancer, we checked the expression levels of PDGFRA and PDGFRB in TRZ_S and TRZ_R derived from the parental BT474 cells." (PMID 36979654, 2023). "Since breast cancer progression is closely linked to EGFR tyrosine kinase signal; it can be speculated that diosgenin-mediated Rap1 signal could attenuate tumor invasion and metastasis; was observed to be modulated via the modulation of three genes i.e., PDGFRB, IGF1R, and FGFR2." (PMID 36686654, 2022). "In breast cancer, it was reported that ITGA11 promoted CAF invasive activity by interacting with PDGFRβ and promoting its downstream JNK activation, leading to the production of tenascin C, a pro-invasive matricellular protein." (PMID 34182990, 2021). "To confirm the role of BRCA1 in controlling Pdgfrβ-Pkcα signaling, we overexpressed WT BRCA1 in two BRCA1-mutant breast cancer cell lines, HCC1937 and SUM149, and a basal-like cell line, MDA-MB231." (PMID 33478572, 2021). "These analyses demonstrate that all six markers identify CAFs in breast cancer, and we therefore designed an antibody panel consisting of the 5 cell surface CAF markers: FAPα, PDGFRα, PDGFRβ, PDPN and CD26." (PMID 34016130, 2021). "Mechanistically, the PDGF-BB–dependent interaction of α11β1 integrin with PDGFRβ activates, through JNK, the production by CAFs of the matricellular protein tenascin C80, which in turn promotes breast cancer cell invasion." (PMID 34131655, 2021).
breast cancer (continued). "To further explore the role of PDGFRβ signaling in activating EMT and promoting tumor initiation and progression, we performed a microarray analysis of mammary tumors from p18−/− and p18−/−;Brca1+/− mutant mice." (PMID 33478572, 2021). "Consistent with this, some evidence suggests that breast cancer cells utilize this pathway in an autocrine fashion, producing PDGF-A/B to self-activate PDGFRβ." (PMID 33478572, 2021). "Perhaps the most intriguing finding from our study was that CL-TNBC, specifically, had much higher expression of CD36, LPL, PDGFRB, FABP4, and PDK4 compared to all other breast cancers, including basal-TNBC." (PMID 31942031, 2020). "One pathway implicated in PDGFRβ regulation is MYC, a transcriptional repressor of PDGFRβ, hence blocking ERK1/2-dependent MYC signaling induces expression and activation of PDGFRβ in breast cancer." (PMID 30777101, 2019). "Since there is accumulating interest in understanding PDGFRβ-mediated resistance mechanisms in various cancers, in this study we sort to investigate its role in resistance to JAK2 inhibition in breast cancer." (PMID 30777101, 2019). "This study aimed to evaluate the expression of PDGFRα, PDGFRβ and ligand PDGF-CC in breast cancer in relation to molecular subtypes and prognosis." (PMID 29380207, 2018). "CDCP1 expression regulation, upon PDGFRβ/ERK1/2 pathway activation, was investigated also in non-breast cancer cells." (PMID 29792166, 2018). "In breast cancer, most studies of the PDGF signalling pathway examine the expression of PDGFRα and PDGFRβ." (PMID 29380207, 2018). "SOX10 suppression contributes to BRAF- and/or MEK-inhibitor resistance in BRAF mutated melanoma, by activating TGFβ signalling to upregulate EGFR and PDGFRB, whilst increasing SOX9 transcript abundance has been observed in breast cancer EMT." (PMID 27852308, 2016). "Furthermore, the highest expression of PDGFRB noted in ADSC TRIDUC1, could verify the overall worse prognosis of this cancer type, due to the finding that high stromal PDGFRB expression is associated with poor prognosis among patients with breast cancer." (PMID 26968831, 2016). "In fact, PDGFRβ, a receptor of PDGF-BB and PDGF-DD, is activated in bone metastasis, and blocking its signaling inhibited growth of breast cancer cells in the bone microenvironment." (PMID 25186085, 2015). "Further evidence for PDGFRβ as a clinically relevant predictive biomarker has been obtained from post hoc analyses of tissue collections from two randomized adjuvant radiotherapy trials in DCIS and stage I/IIA breast cancer." (PMID 38980580, 2024). "For instance, sorafenib is a multikinase inhibitor involved in impairing the autophosphorylation of receptor tyrosine kinases such as VEGFR1, 2, and 3, PDGFRβ, and RET as these receptor tyrosine kinases typically involved in angiogenesis and tumor progression even in breast cancers." (PMID 37910519, 2023). "We uncovered that BRCA1 binds to the GATA3 binding sites in the promoter of PDGFRβ to repress its transcription and that depletion of Brca1 stimulates the expression of PDGFRβ activating the PDGFRβ-PKCα-FRA1 pathway to induce EMT and drive CSC function in breast cancer." (PMID 37353480, 2023). "Moreover, a considerable correlation was found between elevated levels of PDGFRβ expression and reduced OS and disease-free survival (DFS) rates among patients with breast cancer." (PMID 38273859, 2023). "Our previous analysis of open databases showed that ITGA11 expression was correlated positively with PDGFRB, ACTA2, TNC, COL1A1, and COL1A3 in human breast cancer, and the immunostainings showed that α11, PDGFRβ, and TNC were colocalized to CAF subsets in human breast cancer stroma." (PMID 36003785, 2022). "In human breast cancer, isolation of a FAP+PDGFRβ+ CAF subset was shown to promote survival and differentiation of inhibitory Tregs via both a cell contact and paracrine mechanism involving CXCL1245 and was extended to mesenchymal high-grade serous ovarian cancers." (PMID 34740105, 2021).
breast cancer (continued). "Furthermore, ARHGEF1, CFAP65, PDGFRB and CLEC5A were labeled as prognostic marker by the Human Protein Atlas in renal and breast cancer, endometrial cancer, renal and urothelial cancer, and ovarian cancer, respectively." (PMID 34108011, 2021). "Moreover, we queried the mRNA expression of genes in the METABRIC 1584 breast cancer sample sets and found a significant inverse correlation between BRCA1 with PDGFRβ and PKCα mRNA levels." (PMID 33478572, 2021). "Incubation of Gint4.T on PDGFRβ-negative BT-4 T4 breast cancer cells and of Scr on NIH3T3 cells were used as negative controls in parallel analyses." (PMID 32892748, 2020). "(F) Pearson correlation coefficient was calculated between PDGFRB and MYC expression using data derived from panel E. (G) A panel of selected breast cancer and near-normal cell lines was reverse-transfected with 10 nM pooled PDGFRβ siRNAs and cell viability determined after 6 days." (PMID 30777101, 2019). "We found similar results when PDGFRβ was analyzed across breast cancer patients irrespective of subtypes and expression of its ligand PDGFB in chemotherapy treated patients." (PMID 30777101, 2019). "On the other hand, imatinib as a single agent had no clinical effect in PDGFRβ-expressing advanced-stage breast cancer, did not changed the plasma levels of angiogenic molecules, and showed potential immunosuppressive effects." (PMID 27713269, 2010). "PDGFs and their corresponding receptors, PDGFRα and PDGFRβ, exhibit expression in a diverse range of malignant tumors, such as non-small cell lung cancer (NSCLC), gastrointestinal stromal tumor (GIST), pancreatic cancer, breast cancer, ovarian carcinoma and hepatocellular carcinoma." (PMID 41334166, 2025). "Concomitant analyses of six biomarkers, including FAP, CD29 (integrin-β1), α-SMA, FSP1, PDGFRβ, and caveolin, characterized four CAF subsets (from CAF-S1 to CAF-S4) with distinct properties in ovarian and breast cancers (BC)." (PMID 37784082, 2023). "Finally, our results suggest that patients diagnosed with malignant ER+ breast cancer may benefit from combination therapy consisting of IL1R1 and PDGFRβ blockers to enhance the effectiveness of endocrine therapies such as Tam." (PMID 31419632, 2019). "We present novel data on expression of PDGFRα, PDGFRβ and ligand PDGF-CC in primary breast tumours, synchronous lymph node metastasis and asynchronous recurrences in relation to St Gallen Molecular subtypes and long-term follow-up data in a large cohort of primary breast cancer patients." (PMID 29380207, 2018). "In addition, knockdown of PDGFRα or PDGFRβ significantly reduced migration but not proliferation of the claudin-low mammary tumor cells." (PMID 25253994, 2014). "Also, a recent study showed that mRNAs encoding PDGFRα, PDGFRβ and their ligand PDGF-C were highly expressed in basal B subtype of breast cancer cell lines with mesenchymal properties but not in luminal-like cell counterparts with more epithelial features." (PMID 25025175, 2014). "Therefore, it appears that inhibition of PDGFRβ can suppress breast cancer cell migration but does not regulate breast cancer cell proliferation." (PMID 25253994, 2014). "In breast cancer cells, a similar functional relationship between the PDGFR pathway and CXCR4 has been reported, whereby overexpression of PDGF-D, which specifically binds to and activates PDGFRB, was shown to induce CXCR4 expression and promote lymph node metastasis." (PMID 23497290, 2013). "It was shown that breast cancer cells induce PDGFRβ, but not PDGFRα expression in the adjacent ECs." (PMID 27713269, 2010). "For example, whether PDGFRβ signaling activates EMT in a tumor cell autonomous manner and whether PDGFRβ-PKCα signaling is required for survival and for maintaining mesenchymal status of the tumor cells in vivo are key unanswered questions that may inform treatment strategies for breast cancer." (PMID 33478572, 2021).